JMJD8 (jumonji domain containing 8)
Diseases named in the same sentence as JMJD8 in open-access papers (continued):
Sharing a sentence is not in itself a finding about the gene and the disease.
cancer (continued). "Several cancers showed positive correlations between JMJD8 and CD163 intensity, such as LGG." (PMID 35898493, 2022). "We first noticed that JMJD8 was an oncogene in many cancer types." (PMID 35898493, 2022). "At the same time, decreased JMJD8 expressions were observed after anticancer cytokine treatments in several cancer cells, strongly indicating an immunosuppressive role of JMJD8 in most cancers." (PMID 35898493, 2022). "Similarly, in colorectal cancer (CRC), JMJD8 was also reported to boost cancer proliferation and invasion." (PMID 35898493, 2022). "Furthermore, metabolism closely relates to the proliferation of cancer cells and is suppressed by JMJD8 knockdown." (PMID 29133832, 2017). "However, we noticed that several markers were positively correlated with JMJD8 in many cancers." (PMID 35898493, 2022). "Finally, the JMJD8-targeted drugs were sought for specific cancers." (PMID 35898493, 2022). "Despite these findings, it has been shown that reduced JMJD8 expression increases activation of the AKT/NF-B/COX-2 signaling pathway, which promotes cell proliferation and the repair of DSBs in cancer cells." (PMID 36613903, 2022). "To investigate the immunological roles of JMJD8 in the cancer environment, we calculated the ESTIMATE of JMJD8 in pan-cancer." (PMID 35898493, 2022). "Unsurprisingly, 9 cancers, which showed positive correlations between stemness and JMJD8, also presented consistent trends when it came to HRR signature, demonstrating that JMJD8 interplayed with DNA repair-mediated cancer stemness." (PMID 35898493, 2022). "For cancers lacking normal tissues, we compared their JMJD8 expression differences on GEPIA2.0 and UALCAN." (PMID 35898493, 2022). "These presented a comprehensive understanding of JMJD8’s roles in cancers and will provide clues for developing novel targeted therapy." (PMID 35898493, 2022). "We discovered that JMJD8 presented strong positive correlations with M2 macrophages in TGCT, BRCA, and LGG and negative correlations with M1 macrophages and activated CD4+ memory cells in many cancers." (PMID 35898493, 2022). "Whether the relationship between JMJD8 and EGFR is direct or indirect and how JMJD8 regulates EGFR degradation in cancer cells remains unknown." (PMID 33442397, 2021). "JMJD8 is a JmjC domain-containing protein that has not been widely examined, despite its potential role in malignant tumor development." (PMID 33442397, 2021). "JMJD8 had negative correlations with methyltransferases significantly in BRCA and other 4 cancers (MESO, PRAD, SKCM, THYM)." (PMID 35898493, 2022).
tumor (6 papers, 2019 to 2025). "We have characterized the JMJD8-associated immune-infiltrating landscape within the tumor microenvironment of BRCA." (PMID 40761260, 2025). "JMJD8 expression is strongly associated with tumor progression." (PMID 40761260, 2025). "To delineate the role of JMJD8 in sculpting the tumor immune microenvironment, we established its co-expression profile with immunosuppressive infiltrates, revealing significant positive correlations with monocyte/tumor-associated macrophage markers that drive myeloid-driven immune evasion." (PMID 40761260, 2025). "We constructed JMJD8 knockout BRCA cell lines and studied the effects of JMJD8 protein on tumor cell proliferation and anti-tumor immunity at both cellular and animal levels." (PMID 40761260, 2025). "This indicates that high expression levels of JMJD8 exacerbate the immunosuppressive tumor microenvironment, hindering antigen presentation and the initiation of anti-tumor immune responses." (PMID 40761260, 2025). "Nevertheless, the precise mechanisms underlying JMJD8’s involvement in BRCA progression, particularly its functional significance in modulating tumor immune responses, remain insufficiently understood and warrant systematic exploration." (PMID 40761260, 2025). "The average −log10(GI50) of THM-I-94 was −6.65, and in central nervous system (CNS) tumor cell lines, high JMJD8 expression corresponded to higher GI50." (PMID 35898493, 2022). "The cMap tool was utilized to filter the compounds, causing opposite transcriptional alterations to those that increased by high-JMJD8 expression, in 9 different tumor cell lines and the top 30 compounds with JMJD8-targeted potential were displayed." (PMID 35898493, 2022). "JMJD8 was first identified as a tumor suppressor whose knockdown promoted DNA double-strand breaks repair and enhanced the proliferation of non-small lung cancer (NSCLC) and osteosarcoma cell lines." (PMID 35898493, 2022). "It inhibited tumours by suppressing JMJD8 expression and inhibiting the inactivation of the NF-κB pathway in CRC." (PMID 31152315, 2019). "While existing research has characterized aberrant JMJD8 overexpression in tumor tissues and its prognostic relevance across various malignancies, such investigations have predominantly centered on delineating JMJD8’s molecular features and phenotypic correlations." (PMID 40761260, 2025). "Knockdown of JMJD8 activates anti-tumor immune responses to inhibit BRCA proliferation." (PMID 40761260, 2025). "Notably, JMJD8 was more highly expressed in tumor tissues than in adjacent tissues." (PMID 33442397, 2021). "Furthermore, the JMJD8 expression was positively correlated with the infiltration of M2 macrophages in the tumor microenvironment, suggesting that JMJD8 may contribute to the deterioration of the tumor immunosuppressive microenvironment, potentially leading to reduced patient survival." (PMID 40761260, 2025). "This gap in understanding underscores the need for further investigation into JMJD8’s specific functions within the context of BRCA and its potential implications for tumor immunity." (PMID 40761260, 2025). "The positive association with M2 macrophages, which are often implicated in promoting tumor progression and immune suppression, along with the negative association with anti-tumor CD8 T cells, indicates that elevated JMJD8 levels could facilitate an environment conducive to immune escape." (PMID 40761260, 2025). "This discovery suggests that the absence of JMJD8 alleviates the inhibition of the cGAS-STING pathway, thereby activating antitumor immunity and restricting tumor proliferation." (PMID 40761260, 2025).
JMJD8 also shares sentences with these, for which no sentence is quoted: adenocarcinoma (1 paper); bone cancer (1); kidney tumors (1); metastatic cancer (1); osteosarcoma (1).